NPR3 (natriuretic peptide receptor 3)
Diseases named in the same sentence as NPR3 in open-access papers (continued):
Sharing a sentence is not in itself a finding about the gene and the disease.
adrenocortical carcinoma (1 paper, 2022). "In addition, NPR3 was also suggested as favorable to prognosis in adrenocortical carcinoma (ACC: HR = 0.83) but not in stomach adenocarcinoma (STAD: HR = 1.15), bladder urothelial carcinoma (BLCA: HR = 1.11), or breast invasive carcinoma (BRCA: HR = 1.10) where it suggested poor prognosis." (PMID 36159988, 2022).
Autoimmunity (1 paper, 2024). The occurrence of an immune reaction against the organism's own cells or tissues. "In addition, the constitutive degradation of NPR3 monomers by CRL1 leads to preventing autoimmunity without the threat of pathogens." (PMID 38239808, 2024).
blood pressure (1 paper, 2022). "Another genome-wide association study on human primary vascular smooth muscle cells and endothelial cells from different individuals identified that genetic variants at the NPR3 locus are associated with elevated blood pressure." (PMID 36118760, 2022).
CATSHL syndrome (1 paper, 2012). "Since the proband’s phenotype also showed similarity to CATSHL syndrome, caused by a loss-of-function mutation in the Fgfr3 gene, except for the absence of neurological symptoms, the Fgfr3 gene was analyzed as well as the natriuretic peptide precursor C (Nppc), Npr2, and Npr3 genes." (PMID 22870295, 2012).
hyperopia (1 paper, 2016). A refractive error in which rays of light entering the eye parallel to the optic axis are brought to a focus behind the retina, as a result of the eyeball being too short from front to back. "NPR3, a gene that shows growth-specific expression shifts in the tree shrew sclera, was also up-regulated during hyperopia induction." (PMID 27625591, 2016).
hypotension (1 paper, 2023). "In mouse, deletion of Npr3 causes systemic hypotension and skeletal deformities, including hunched backs, dome-shaped skulls, elongated long bones and vertebral bodies." (PMID 37162198, 2023).
injury (1 paper, 2021). Damage inflicted on the body as the direct or indirect result of an external force, with or without disruption of structural continuity. "The current results indicate that NPR3 exhibits indirect neuroprotection via vascular protection after neonatal HI brain injury." (PMID 34445671, 2021).
Kyphosis (1 paper, 2016). Exaggerated anterior convexity of the thoracic vertebral column. "In conclusion, we have established a novel mouse model for kyphosis associated with lengthened vertebrae and long bones that harbors a Tyr209Asn mutation in NPR3." (PMID 27959934, 2016). "Thus, we established a model of kyphosis due to a novel NPR3 mutation, in which loss of plasma membrane NPR3 expression results in increased MAPK pathway activation, causing elongation of the vertebrae and resulting in kyphosis." (PMID 27959934, 2016). "In addition, the in vitro consequences of two other ENU-induced NPR3 missense mutations, His168Asn and Ile384Phe that were reported to be associated with kyphosis in Strigosus (Stri) and Eel mice, respectively, but whose cellular effects were not reported, were similarly assessed." (PMID 27959934, 2016).
medulloblastoma (1 paper, 2020). A malignant, invasive embryonal neoplasm arising from the cerebellum. "The detection of over-expressed NPR3 in the CTCs from a Group 3 Medulloblastoma was another evidence in supporting the specificity of CTCs isolated by IMLs." (PMID 33208163, 2020). "What’s more, CTCs from a patient diagnosed with medulloblastoma were revealed with over-expressed NPR3 by RT-PCR, which was consistent with immunohistochemistry staining of NPR3 protein in tumor tissue." (PMID 33208163, 2020). "What’s more, NPR3 overexpression is a characteristic phenomenon in identification of Group 3 Medulloblastoma." (PMID 33208163, 2020).
metastatic tumors (1 paper, 2017). "Additionally, NPR3 expression is elevated in MRCCAT1 knockdown lung metastatic tumors." (PMID 28659173, 2017).
pancreatic cancer (1 paper, 2022). "Overexpressed pancreatic cancer receptors include SLC2A1, MET, IL1RAP, NPR3, GABRP, SLC6A6, and TMPRSS4." (PMID 35359382, 2022). "We identified 7 highly expressed pancreatic cancer cell surface receptors (MET, NPR3, IL1RAP, SLC2A1, SLC6A6, GABRP, and TMPRSS4) in all the analyzed datasets." (PMID 35359382, 2022). "The L5 proteins of 3 serotypes of adenovirus HAdV2, HAdV3, and HAdV5 are docked with the seven highly expressed pancreatic cancer receptors SLC2A1, MET, IL1RAP, NPR3, GABRP, SLC6A6, and TMPRSS4." (PMID 35359382, 2022).
periodontitis (1 paper, 2022). An acute or chronic inflammatory process that affects the tissues that surround and support the teeth. "In addition, our results showed the genes of TNFRSF1B and NPR3 were hypo-methylated in the periodontitis." (PMID 35491409, 2022).
renal cell carcinoma (1 paper, 2022). "NPR3 was found to be a favorable prognostic factor in this study and was differently associated with prognosis in different subtypes of renal cell carcinoma." (PMID 36159988, 2022). "Third, although this study found that four genes (COL7A1, LCTL, NPR3, and ZFHX4), had a large impact on the prognosis of renal cell carcinoma and analyzed their relationship with survival in multiple cancers, the specific molecular biology and cell biology mechanisms need to be further investigated." (PMID 36159988, 2022).
sarcoma (1 paper, 2022). A usually aggressive malignant neoplasm of the soft tissue or bone. "The 1-year AUC values for TCGA training cohort of the SAGRI constructed using the four sarcoma-like differentiation-related genes (COL7A1, LCTL, NPR3, ZFHX4) were 0.725 in the training set, 0.712 in the internal validation set, and 0.770 in the external validation set." (PMID 36159988, 2022).
infection (20 papers, 2013 to 2025). The state of being infected such as from the introduction of a foreign agent such as serum, vaccine, antigenic substance or organism. "Developing flowers of homozygous npr3 mutants are dramatically more resistant to infection by the pathogenic bacterium Pseudomonas syringae, suggesting a role of NPR3 as a repressor of NPR1-mediated defense response with a novel role in flower development." (PMID 24314063, 2013). "Similarly, nuclear NPR1 levels were lower at the infection site of an avirulent pathogen causing cell death by NPR3/4-mediated degradation." (PMID 34911942, 2021). "As SA levels rise during pathogen infection, its binding to NPR3/NPR4 releases transcriptional repression of defense genes during pathogen infection, whereas the binding of SA to NPR1 further activates the expression of defense genes." (PMID 40343347, 2025). "A high SA concentration at the infection site binds NPR3, thus promoting NPR1 degradation, leading to plant cell death at the infection site and hindering the spread of pathogen infection." (PMID 31653915, 2019). "(c) At the site of pathogen attack, high SA levels active NPR3‐directed NPR1 destruction, thereby lifting NPR1‐repression of HR causing cell death at the infection site." (PMID 31245748, 2018). "In a homologous test system, a cacao miRNA efficiently reduced endogenous TcNPR3 mRNA expression, and this in turn resulted in increased resistance to pathogen infection, consistent with the function of NPR3 as a repressor of the defense response." (PMID 24314063, 2013). "To explore the effect of NPR3 expression on the ability of cacao leaves to respond and defend against pathogen infection, we inoculated the leaves with the cacao pathogen Phytophthora capsici." (PMID 24314063, 2013). "Three days after infection, lesions were formed in both control and NPR3-microRNA expressing leaf pieces." (PMID 24314063, 2013). "On the one hand, when the concentration of SA in plants is very low, NPR3/4 block the expression of genes downstream of SA; the transcriptional repression effect of NPR3/4 on SA downstream genes is relieved based on elevated SA concentrations during pathogen infection." (PMID 36834798, 2023). "FBLN2 or NPR3 deficiency did not influence MSCs proliferation within 7 days post-infection (Data not shown)." (PMID 37543430, 2023). "Moreover, high expression of NPR3 in atg4a4b may accelerate the degradation of NPR1 during AvrRpt2 infection." (PMID 32708160, 2020). "Similarly to the results obtained using the SA biosensor, upon Psm ES4326 infection, the 17 sln npr1-3 mutants accumulated dramatically lower levels of free SA and the two isn npr1-3 mutants produced higher levels of free SA than the npr-3 mutant." (PMID 25610446, 2014). "On one hand, NPR3 and NPR4 suppress defense gene expression when SA levels are low, but when SA levels rise due to pathogen infection, NPR3 and NPR4 activities are reduced, and the transcriptional repression of SA-responsive genes is relaxed." (PMID 38068630, 2023). "NPR1, NPR3, and NPR4 bind SA with varying affinities and play a role in binding to downstream TGA transcription factors in response to pathogen infections." (PMID 36834798, 2023). "When the biotic and abiotic infection, SA will combine with its receptors (NPR1, NPR3, and NPR4) and induce the expression of PR protein, which leads to trigger the immune responses." (PMID 35003927, 2021). "It has been reported that the RPS2, a CC-NB-LRR-type R-gene, induced NPR3 and NPR4 and activated JA synthesis via the degradation of JAZ1 proteins in response to hemibiotrophic pathogen infection." (PMID 32121557, 2020). "The expression of NPR1, NPR3 and NPR4 in WT and atg4a4b increased, and then declined gradually with AvrRpt2 infection time at the initial stage of infection." (PMID 32708160, 2020).
infection (continued). "This degradation is tightly controlled by the SA-mediated differential interactions with the ubiquitin E3 ligase adapters NPR3 and NPR4 so that PCD only occurs at the site of infection." (PMID 27513560, 2016). "Upon pathogen infection, SA is synthesized through the isochorismate pathway and perceived by two groups of receptors, NPR1 and NPR3/NPR4, to regulate plant systemic acquired resistance (SAR), PAMPs-triggered immunity (PTI), and effector-triggered immunity (ETI)." (PMID 38186590, 2023).
tumor (16 papers, 2014 to 2025). "THBS2 (thrombospondin 2), BASP1 (brain acid soluble protein 1), and NPR3 (natriuretic peptide receptor 3) are tumor-suppressor genes, for which downregulation is associated with poor prognosis." (PMID 36980828, 2023). "For example, in CRC, the lncRNA BCYRN1 promotes tumour cell proliferation by upregulating NPR3, which confirms that NPR3 is a promoter in CRC29." (PMID 37076508, 2023). "Among the mitochondrial dysfunction-related genes, NPR3 mediates natriuretic peptides degradation and was proved to act as a tumor suppressor in certain types of cancers." (PMID 36468038, 2022). "NPR3 mediates natriuretic peptides degradation, was reported to act as a tumor suppressor or promoter in some types of cancer." (PMID 36207572, 2022). "NPR3 is involved in the pathogenesis of cancer and can act as both a tumor suppressor or promoter in some types of cancer." (PMID 35558081, 2022). "NPR3 has previously been shown to play a pivotal role in tumor proliferation and metastasis by being negatively coupled to adenylyl cyclase and MAPK signaling pathways." (PMID 28659173, 2017). "The tumours from which the cell lines were derived have been assigned to MB molecular subtypes using IHC for β-catenin, Gli1, NPR3 and KCNA1, and sequencing of the β-catenin gene (CTNNB1)." (PMID 24887326, 2014). "The NPR3 overexpression stimulated the migration and growth of GC cell lines, indicating that NPR3 may function as a promoter of tumor growth in GC progression." (PMID 38807601, 2024). "For example, the high expression of NPR3 gene in CSF CTCs was consistent with that of tumor tissue." (PMID 33208163, 2020). "Of note, primary PCa tumours showed high JAG1, GP2, GLO1, NPR3, VGLL3, CHRNA2 and SEMA3F mRNA levels in primary PCa tissue samples." (PMID 40219635, 2025). "A four‐mRNA signature (CHRNA2, NPR3, VGLL3 and PAH) was found in primary tumour tissue samples from pN1 PCa patients, and then it was validated using the TCGA‐PRAD and GSE220095 datasets." (PMID 40219635, 2025). "Resistance to cisplatin has been initially observed in yeast S. cerevisiae for Npr2 and Npr3 deletion mutants (NPRL2 and NPRL3 homologs, respectively), years before GATOR1 components were suggested to be tumor suppressors." (PMID 41469472, 2025). "Of notice, miR‐125a‐3p, miR‐663b and miR‐664a‐5p were upregulated in pN1 PCa tumours and showed a negative correlation with NPR3." (PMID 40219635, 2025).
cancer (12 papers, 2019 to 2025). A tumor composed of atypical neoplastic, often pleomorphic cells that invade other tissues. "Thus, NPR3 might be a viable therapeutic target to decrease cancer and cardiovascular diseases risk in OSA patients." (PMID 36468038, 2022). "As regards the top genes that turned out to be downregulated by AFB1, the natriuretic peptide receptor 3 (NPR3) seems of particular interest for carcinogenesis, as its inhibition in renal cells has been shown to promote cancer development." (PMID 32610656, 2020). "We also show that overexpression of musclin, or its receptor, natriuretic peptide receptor 3 (Npr3), protects muscles from wasting during cancer." (PMID 31614775, 2019). "The 13 overexpressed genes were reported to play a role in RCC: PAX2, NAT8, GBA3, SLC22A2 other cancer types: AOC1, HAO2, TMEM27, cell death (NPR3) or kidney metabolism: TMEM171, CYS1." (PMID 31150395, 2019). "Moreover, the expression levels of 13 out of 16 genes (except RGPD8, NPR3, and KDM5C) differed according to the cancer stage." (PMID 31963294, 2020).
cardiovascular disease (9 papers, 2017 to 2025). "Both heterozygous and homozygous knockout mice for Npr3 exhibit alterations in cardiovascular system, and several evidences suggest that mutations in Npr3 may lead to cardiovascular diseases." (PMID 31234560, 2019). "Recent genetic research revealed the association of the NPR3 locus with blood pressure in patients, suggesting plausible pathological relevance of NPR3 in clinical cardiovascular disease." (PMID 29728596, 2018).
metabolic disease (5 papers, 2017 to 2023). A congenital disorder (due to inherited enzyme abnormality) or acquired (due to failure of a metabolically important organ) disorder resulting from an abnormal metabolic process. "NPR3 is a clearance receptor of natriuretic peptides and has been reported to be involved in regulation of cell metabolism and progression of metabolic diseases." (PMID 35841070, 2022).
kidney disease (2 papers, 2024 to 2025). "Further studies, including compound and dose optimization as well as finding the right route of delivery are needed to further interrogate and validate the therapeutic potential of NPR3 targeting to treat kidney disease." (PMID 38782980, 2024). "In this study we examined the expression of NPR3 in kidney tissue and explored its involvement in renal physiology and disease by generating podocyte-specific knockout mice (NPR3podKO) as well as by using an NPR3 inhibitor (NPR3i) in rodent models of kidney disease." (PMID 38782980, 2024). "In conclusion, these results suggest that NPR3 may contribute to kidney disease progression." (PMID 38782980, 2024).
NPR3 also shares sentences with these, for which no sentence is quoted: diabetes (7 papers); Insulin resistance (6); atherosclerosis (5); coronary artery disease (5); irritable bowel syndrome (5); Hyperinsulinemia (4); pulmonary hypertension (4); Arrhythmia (3); colitis (3); Constipation (3); ischemia (3); cardiac arrhythmias (2); cardiac disease (2); cardiac ischemia (2); COVID-19 (2); focal segmental glomerulosclerosis (2); inflammatory bowel disease (2); Myocardial fibrosis (2); pulmonary fibrosis (2); acute coronary syndrome (1); adjustment disorder (1); allergic asthma (1); Anxiety (1); arteritis (1); asthma (1); bladder urothelial carcinoma (1); breast invasive carcinoma (1); depression (1); diabetic kidney disease (1); dyslipidemia (1).
A further 35 diseases each share a sentence with NPR3 in 1 paper.